RALGAPA1 (Ral GTPase activating protein catalytic subunit alpha 1)
Description:
Catalytic subunit of the heterodimeric RalGAP1 complex which acts as a GTPase activator for the Ras-like small GTPases RALA and RALB.
Synonyms: GRIPE; GARNL1; KIAA0884; TULIP1; DKFZp667F074; RalGAPalpha1; NEDHRIT; p240
Tractability: PROTAC: ubiquitination databases record sites on it; its protein half-life has been measured.
Gene: Protein-coding gene on chromosome 14 (35,538,352 to 35,809,304, reverse strand). Ensembl gene ENSG00000174373.
Subcellular location: Cytoplasm; Nucleus
Subcellular location (Human Protein Atlas): Cytosol; Mid piece; Mitochondria; Principal piece
Pathways (Reactome):
Signal Transduction: RHOH GTPase cycle
Gene Ontology:
Molecular function: protein heterodimerization activity; GTPase activator activity
Biological process: activation of GTPase activity; small GTPase-mediated signal transduction; regulation of small GTPase mediated signal transduction
Cellular component: cytoplasm; nucleus
Genetic constraint (gnomAD): Loss-of-function variants: 32 observed, 147.32 expected, observed/expected ratio (o/e) 0.22, 90% interval 0.16 to 0.29. The upper end of that interval is the gene's LOEUF score, 0.29, which puts it in group 1 of 6, group 1 being the genes least tolerant of losing a copy. Missense variants: 1,417 observed, 2,088.6 expected, observed/expected ratio (o/e) 0.68, 90% interval 0.65 to 0.71. Synonymous variants: 605 observed, 717.24 expected, observed/expected ratio (o/e) 0.84, 90% interval 0.79 to 0.9.
Homologues: Orthologues: macaque RALGAPA1 (97% identical), chimpanzee RALGAPA1 (97% identical), pig RALGAPA1 (96% identical), guinea pig RALGAPA1 (95% identical), dog RALGAPA1 (94% identical), rabbit RALGAPA1 (94% identical), rat Ralgapa1 (93% identical), mouse Ralgapa1 (76% identical), tropical clawed frog ralgapa1 (66% identical), zebrafish ralgapa1 (61% identical), Drosophila melanogaster CG5521 (27% identical), Caenorhabditis elegans hgap-1 (14% identical). Paralogues in human: RALGAPA2 (40% identical), TSC2 (13% identical).
Diseases named in the same sentence as RALGAPA1 in open-access papers:
RALGAPA1 is named in the same sentence as 19 diseases in open-access papers, as found by Europe PMC text mining. Sharing a sentence is not in itself a finding about the gene and the disease. The quoted sentences say what the papers report.
epilepsy (3 papers, 2021 to 2025). A brain disorder characterized by episodes of abnormally increased neuronal discharge resulting in transient episodes of sensory or motor neurological dysfunction, or psychic dysfunction. "Human patients with loss-of-function variants in RALGAPA1 develop psychomotor disability and early-onset epilepsy." (PMID 37628572, 2023). "Splicing variants of Ralgapa1 were detected in zebrafish, annotated to variants in human and mouse, and differentially associated with epilepsy." (PMID 34680965, 2021). "RalGAPA1 deficiency leads to increased RalA activity, and human patients with biallelic RALGAPA1 variants display neuromuscular abnormalities that later develop into severe psychomotor disability and early-onset epilepsy (OMIM #618797)." (PMID 37628572, 2023).
cerebellar ataxia (2 papers, 2023 to 2025). A neurological syndrome characterized by clumsy and uncoordinated movement of the limbs, trunk, and cranial muscles. "In the present study, we identified a ~4.8 kb genomic deletion within the RALGAPA1 gene in Belgian shepherd dogs with cerebellar ataxia." (PMID 37628572, 2023). "RALGAPA1 gene defects need to be considered for Malinois puppies presenting with cerebellar ataxia." (PMID 39969014, 2025).
cardiomyopathy (1 paper, 2022). A disease of the heart muscle or myocardium proper. "Together, these data suggest that the RalGAPα1 complex might play a role in pressure overload-induced cardiomyopathy." (PMID 35879328, 2022).
co-infection (1 paper, 2025). "Thus, the lower mutation rate in the LAC-TB group may suggest either selective pressure from the MTB infection on RALGAPA1-mutated cells or an alternative tumor development pathway due to co-infection." (PMID 40061944, 2025). "RALGAPA1 mutations may be critical for LAC progression without MTB, while alternative oncogenic pathways could be activated during co-infection, reducing dependence on RALGAPA1 mutations for tumor development." (PMID 40061944, 2025).
heart failure (1 paper, 2022). Inability of the heart to pump blood at an adequate rate to meet tissue metabolic requirements. "RalGAPα1 is induced by pressure overload, and its deficiency causes cardiac dysfunction and exacerbates pressure overload-induced heart failure." (PMID 35879328, 2022). "Deletion of RalGAPα1 also exacerbated TAC-induced cardiac remodeling with upregulation of cardiac fibrosis and increased expression of heart failure markers such as Anp, Bnp, Col1a1 and Col3a1 in the RalGAPα1-cKO hearts as compared to the control hearts." (PMID 35879328, 2022).
hereditary ataxia (1 paper, 2023). An instance of an atactic disorder that is caused by an inherited genomic modification in an individual. "We provide an initial clinical and pathological characterization of a new hereditary ataxia in Belgian shepherd dogs and identify RALGAPA1:c.6080-2893_6944+1003del as the likely causative variant for the observed phenotype." (PMID 37628572, 2023).
Insulin resistance (1 paper, 2020). Increased resistance towards insulin, that is, diminished effectiveness of insulin in reducing blood glucose levels. "Deficiency of PKBα/β caused insulin resistance in mouse heart, and the abundance of their substrates including AS160, RalGAPα1, RalGAPα2, and TSC2 in the PAS immunoprecipitates was substantially lower for PKBα/β-deficient mouse heart relative to wild-type mouse heart upon insulin stimulation." (PMID 32367034, 2020).
Obesity (1 paper, 2022). Accumulation of substantial excess body fat. "Thus, further testing will be needed to determine whether the RALGAPA1 is associated with obesity in an independent Taiwanese cohort." (PMID 35051171, 2022).
tumor (3 papers, 2018 to 2025). "To provide structural insights into the role of RalGAP complexes as tumor suppressors, we searched for missense mutations in the RALGAPA1, RALGAPA2, and RALGAPB genes in cancer patients." (PMID 40738882, 2025). "Further research is needed to understand the specific mechanisms behind the observed differences in RALGAPA1 mutations and their implications for tumor progression and treatment strategies in LAC-TB patients." (PMID 40061944, 2025).
infection (1 paper, 2024). The state of being infected such as from the introduction of a foreign agent such as serum, vaccine, antigenic substance or organism. "To further probe the impact on HMA, we used an siRNA approach to knock down RalGAPα1 transcript levels followed by infection with Type II:MAF1b parasites." (PMID 38141762, 2024).
RALGAPA1 also shares sentences with these, for which no sentence is quoted: cancer (2 papers); neurodevelopmental disorder (2); Basal ganglia calcification (1); breast carcinoma (1); ciliopathies (1); endometriosis (1); genetic disease (1); lung carcinoma (1); neurodevelopmental disorder with hypotonia, neonatal respiratory insufficiency, and thermodysregulation (1).